KLK8 (kallikrein related peptidase 8)
Description:
Serine protease which is capable of degrading a number of proteins such as casein, fibrinogen, kininogen, fibronectin and collagen type IV. Also cleaves L1CAM in response to increased neural activity. Induces neurite outgrowth and fasciculation of cultured hippocampal neurons. Plays a role in the formation and maturation of orphan and small synaptic boutons in the Schaffer-collateral pathway, regulates Schaffer-collateral long-term potentiation in the hippocampus and is required for memory acquisition and synaptic plasticity. Involved in skin desquamation and keratinocyte proliferation. Plays a role in the secondary phase of pathogenesis following spinal cord injury.
Synonyms: NP; NRPN; PRSS19; TADG14; HNP; neuropsin; ovasin
Tractability: Small molecule: a high-quality ligand is known. Antibody: UniProt places it where antibodies can reach, with high confidence; its Gene Ontology location is reachable by antibodies, with high confidence; UniProt predicts a signal peptide or a membrane-spanning region. PROTAC: a small molecule that binds it is known.
Target class: Serine protease; Enzyme; Serine protease PA clan; Serine protease S1A subfamily; Protease
Gene: Protein-coding gene on chromosome 19 (50,996,007 to 51,002,711, reverse strand). Ensembl gene ENSG00000129455.
Subcellular location: Secreted; Cytoplasm
Subcellular location (Human Protein Atlas): Vesicles; Predicted to be secreted
Pathways (Reactome):
Developmental Biology: Formation of the cornified envelope
Gene Ontology:
Molecular function: protein binding; serine-type endopeptidase activity; peptidase activity
Biological process: keratinocyte proliferation; memory; neuron projection morphogenesis; protein maturation; regulation of synapse organization; response to wounding; proteolysis
Cellular component: cytoplasm; serine protease inhibitor complex; extracellular region; secretory granule
Genetic constraint (gnomAD): Loss-of-function variants: 22 observed, 32.3 expected, observed/expected ratio (o/e) 0.68, 90% interval 0.49 to 0.97. The upper end of that interval is the gene's LOEUF score, 0.97, which puts it in group 4 of 6, group 1 being the genes least tolerant of losing a copy. Missense variants: 301 observed, 345.48 expected, observed/expected ratio (o/e) 0.87, 90% interval 0.79 to 0.96. Synonymous variants: 137 observed, 134.75 expected, observed/expected ratio (o/e) 1.02, 90% interval 0.88 to 1.17.
Homologues: Orthologues: chimpanzee KLK8 (100% identical), dog KLK8 (77% identical), rabbit KLK8 (76% identical), pig KLK8 (75% identical), guinea pig KLK8 (72% identical), mouse Klk8 (72% identical), rat Klk8 (72% identical), tropical clawed frog klk1 (40% identical), Drosophila melanogaster CG12256 (25% identical), Drosophila melanogaster CG32808 (25% identical), Drosophila melanogaster CG4477 (25% identical), Drosophila melanogaster Send2 (25% identical), and 7 more. Paralogues in human: KLK12 (46% identical), KLK11 (45% identical), KLK14 (45% identical), KLK5 (45% identical), KLK7 (44% identical), KLK1 (42% identical), KLK2 (42% identical), KLK3 (39% identical), KLK4 (38% identical), TMPRSS4 (31% identical), PRSS58 (29% identical), PRSS54 (20% identical).
Diseases named in the same sentence as KLK8 in open-access papers:
KLK8 is named in the same sentence as 86 diseases in open-access papers, as found by Europe PMC text mining. Sharing a sentence is not in itself a finding about the gene and the disease. The quoted sentences say what the papers report.
ovarian carcinoma (19 papers, 2002 to 2024). A malignant neoplasm originating from the surface ovarian epithelium. "Previous studies have reported that KLK8 was a prognostic factor in various cancer types, including cervical cancer, lung cancer, and ovarian cancer." (PMID 38273291, 2024). "But in other tumors, such as ovarian cancer, the elevated expression of KLK8 is a favorable prognostic marker." (PMID 34395235, 2021). "For example, elevated expression of KLK8 is observed in ovarian cancer, oral squamous cell carcinoma, salivary gland tumours and cervical cancer and indicates unfavourable prognosis in lung cancer and breast cancer." (PMID 34552064, 2021). "KLK8 (Kallikrein Related Peptidase 8) has presented its research value in the prognosis of various cancers, such as lung cancer, ovarian cancer, breast cancer, colon cancer, and rectal cancer." (PMID 33195688, 2020). "Pointing to potential cancer-type specific effects as described for KLK6, KLK8 is a favorable prognostic indicator in ovarian cancer, but an unfavorable indicator in lung cancer." (PMID 26231762, 2015). "KLK8 protein present in blood (serum) indicates a favorable prognosis for the ovarian cancer patient while elevated protein levels of KLK5, 6, 10 and 11 are markers of a poor clinical outcome." (PMID 24294176, 2013). "KLK8 was upregulated in colorectal cancer and ovarian cancer while underexpressed in esophageal and cervical cancer." (PMID 23343470, 2013). "Using this approach, we have previously reported that several candidates including hepsin, stratum corneum chymotryptic enzyme (SCCE/KLK7), protease M (KLK6), TADG-12, and TADG-14 (KLK8) are abundantly expressed in ovarian cancers." (PMID 15611789, 2005). "However, KLK8 upregulation predicts favourable prognosis in non-small cell lung cancer and ovarian cancer." (PMID 34552064, 2021). "This full-length KLK8 expression is an independent and favorable marker for ovarian cancer." (PMID 33150763, 2020). "Similarly, the human KLK8 gene was cloned from human cDNA2, while expression of the KLK8 protein was detected in skin, esophagus, tonsils, salivary gland, breast milk, cervico-vaginal fluid, and in ovarian cancer extracts." (PMID 30013126, 2018). "KLK8, one of the members of the KLKs family, is a synaptic, plasticity-modulating extracellular serine protease, involved with several malignant diseases, including ovarian cancer, cervical cancer, breast cancer, colorectal cancer, oropharyngeal cancer, gastric cancer, pancreatic cancer, and NSCLC." (PMID 38273291, 2024). "In contrast, KLK8 and KLK9 expression have been reported to be favorable prognosis in ovarian cancer." (PMID 24510347, 2014). "The hierarchical clustering revealed a group of proteins that have previously been reported to be expressed at elevated levels in ovarian cancer serum samples, including: CA125 (MUC16), HE4, MSLN, MK, KLK8, KLK11, NECT4, FOLR1, as well as KLK13, KLK14, and IL6." (PMID 35804849, 2022). "Among these, KLK6, KLK7, KLK8, and KLK10 showed the highest statistical significance in ovarian cancer effusions over other cancer groups, suggesting that these kallikreins might be useful biomarkers in differential diagnosis of ovarian cancer." (PMID 23319948, 2012). "Furthermore, KLK8 and KLK9 expression are higher in ovarian cancer of better prognosis." (PMID 11986781, 2002).
breast carcinoma (8 papers, 2004 to 2025). "For example, KLK8 has been recognized as a poor prognostic marker for lung and breast cancer." (PMID 34395235, 2021). "The mechanism of KLK8 gene silencing in breast cancer has not been reported, though alternative splice variants of the gene which influence prognosis have been reported in lung cancer." (PMID 22436421, 2012). "Our analysis of public datasets confirmed that high KLK8 expression correlates with poor patient outcomes in 10 out of 13 human cancer types examined for pancreatic, endometrial, and breast cancers, as well as for clear cell renal cell carcinoma and urothelial bladder carcinoma." (PMID 40064965, 2025).
depression (8 papers, 2019 to 2025). "Tissue kallikrein-related peptidase 8 (KLK8), a secreted serine protease, has been implicated in the pathogenesis of depression- and anxiety-related behaviors across various etiologies, however the underlying mechanisms remain largely unexplored." (PMID 40521191, 2025). "In the present study, we first examined the effects of KLK8 deficiency on hippocampal microglial activation, neuroinflammation, and depression-like behaviors in streptozotocin (STZ)-induced diabetic mice." (PMID 40521191, 2025). "Among these DEGs, KLK8, a gene implicated in the pathogenesis of stress-induced depression-like behaviors 7, 8, 11, was significantly upregulated in the hippocampus obtained from the STZ-induced diabetes group compared with those from the control group." (PMID 40521191, 2025). "Transgenic overexpression of KLK8 exacerbated, whereas KLK8 deficiency attenuated CUMS-induced depression-like behaviors and hippocampal neuronal apoptosis." (PMID 37076499, 2023). "It was found that depression-like behavior in CUMS-induced mice was associated with hippocampal KLK8 upregulation." (PMID 37076499, 2023). "The present study reported for the first time that increased KLK8 protein levels in the hippocampus was associated with CUMS-induced depression-like behaviors." (PMID 37076499, 2023). "The present study aimed to explore the potential function of KLK8 in hippocampal neuronal cell apoptosis associated with depressive disorders in rodent models of chronic unpredictable mild stress (CUMS)-induced depression." (PMID 37076499, 2023). "Taken together, these results indicated that KLK8 overexpression was exacerbated, whereas KLK8 deficiency attenuated the depression-like behaviors in experimental rodent models of CUMS." (PMID 37076499, 2023). "KLK8 has been implicated in the pathogenesis of several psychiatric disorders, such as anxiety, depression, and schizophrenia." (PMID 37076499, 2023). "Previous studies have implicated KLK8 in the pathogenesis of several psychiatric disorders, including anxiety and depression." (PMID 37076499, 2023). "Apart from differences in cohort design (monozygotic twins vs population-based), this follow-up study carries other differences in comparison with the EWAS reporting the association between DNAm in KLK8 and depression symptomatology." (PMID 34715912, 2021). "In the PRISME cohort, we observed a tendency of higher DNAm levels at CpG1 in KLK8 promoter region to be associated with more severe depression symptoms." (PMID 34715912, 2021). "KLK8 is thought to be associated with epilepsy, depression, and multiple sclerosis, but until recently, almost nothing was known in the context of AD." (PMID 34930454, 2021). "Recently, an epigenome-wide association study of monozygotic twins identified an association between DNAm status in the KLK8 (neuropsin) promoter region and severity of depression symptomatology." (PMID 34715912, 2021). "The association between depression severity score and variation of DNAm levels in the KLK8 promoter region was supported by 7 CpG sites with p value < 0.05 in the GSMS cohort." (PMID 34715912, 2021). "Along this line, increased expression levels of KLK8 in blood were shown to be significantly associated with recurrent depression diagnosis in comparison with patients with first episode of depression, and to healthy controls." (PMID 34715912, 2021). "We further tested the association between KLK8 DNAm levels and depression-related phenotypes in four methylomic cohorts, with data on CpG1 site available in NESDA and GSMS, and on CpG2 site in NESDA, GSMS, and BioMom." (PMID 34715912, 2021). "Adjusting for sex and age in the regression models should minimize impact of these demographic cohort differences on detecting the association between depression symptomatology and KLK8 DNAm levels." (PMID 34715912, 2021).
depression (continued). "This is especially interesting when considering that both blood KLK8 mRNA and methylation status have been associated with depression symptomatology." (PMID 32414324, 2020). "Increased expression of KLK8 has also been implicated in schizophrenia, bipolar disorder, and depression." (PMID 32655372, 2020). "However, to the best of our knowledge, only one study reported that the severity of depression-like behaviors induced by chronic stress or chronic corticosterone injection is reduced in KLK8-deficient mice." (PMID 37076499, 2023). "In this study, we aimed at testing if epigenetic variation in the KLK8 promoter region, recently implicated with depression symptomatology through EWAS, is associated with depression severity scores and depression case–control status first in an independent clinical PRISME cohort." (PMID 34715912, 2021). "Moreover, environmental risk factors for depression, like acute stress, lead to increased KLK8 expression levels in hippocampus, where it plays a role in proteolysis of trophic factors and synaptic plasticity." (PMID 34715912, 2021). "A recent epigenome-wide association study (EWAS) performed in blood of 724 Danish monozygotic twins reported DNAm levels in the promoter region of Kallikrein Related Peptidase 8 (KLK8, neuropsin) to be associated with severity of depression symptomatology in the general population." (PMID 34715912, 2021). "An association between depression symptomatology score in the general population and blood DNA methylation levels in the promoter region of KLK8 was recently identified in a large cohort of monozygotic Danish twins, supporting the implication of KLK8 in depression symptomatology." (PMID 32414324, 2020). "Therefore, it cannot be excluded that additional mechanisms, such as synaptic, morphological, and electrophysiological disturbances, may also contribute to the improvement of depression symptoms observed in KLK8-deficient mice exposed to CUMS." (PMID 37076499, 2023). "Taken together, these findings suggest that aerobic exercise reverses KLK8 upregulation and mitigates depression-like behaviors, microglia activation, and neuroinflammation in STZ-induced diabetic mice." (PMID 40521191, 2025). "Nevertheless, the connection between KLK8 and depression related to diabetes, particularly its role in modulating microglial cells, remains largely undetermined." (PMID 40521191, 2025). "Several studies have indicated the crucial role of KLK8 in the pathogenesis of depression- and anxiety-related behaviors resulting from different etiologies 9-11." (PMID 40521191, 2025). "Previous studies have demonstrated that KLK8 inactivation protected against chronic stress-induced depression-like behaviors by alleviating hippocampal glutamate dysregulation 10 and neuronal apoptosis." (PMID 40521191, 2025). "Thus, inhibiting the KLK8/Met pathway through genetic or pharmaceutical approaches to mitigate neuroinflammation may offer potential therapeutic strategies for diabetes-associated depression." (PMID 40521191, 2025). "Many studies have revealed a correlation between an increase in the levels of KLK8 and the pathogenesis of various diseases, such as pancreatic cancer and depression." (PMID 39578836, 2024). "In summary, the present study provided several lines of evidence supporting a new pro-apoptotic mechanism in the hippocampus during the pathogenesis of CUMS-induced depression via the upregulation of KLK8." (PMID 37076499, 2023). "Using KLK8 transgenic rats, the present study first examined the effect of KLK8 overexpression on CUMS-induced depression-like behaviors." (PMID 37076499, 2023). "Taken together, although these findings prompted us to consider antibody-mediated KLK8 inhibition as a promising therapeutic strategy against depression, the anti-KLK8 antibody must be used with great caution due to its side effects." (PMID 37076499, 2023).
depression (continued). "Collectively, this study identified a new pro-apoptotic mechanism in the hippocampus during the pathogenesis of CUMS-induced depression via the upregulation of KLK8, and raised the possibility of KLK8 as a potential therapeutic target for depression." (PMID 37076499, 2023). "KLK8 deficiency significantly alleviated, whereas transgenic overexpression of KLK8 exacerbated CUMS-induced depression-like behaviors." (PMID 37076499, 2023). "First, KLK8 transgenic rats and KLK8 knockout mice were used to assess the impact of KLK8 overexpression and KLK8 deficiency on CUMS-induced depression, respectively." (PMID 37076499, 2023). "In the present study, we first examined the hippocampal expression of KLK8 in a mouse model of chronic unpredictable mild stress (CUMS)-induced depression." (PMID 37076499, 2023). "The same direction of effect was observed for seven CpG sites in the KLK8 promoter region in the much larger GSMS cohort, where higher DNAm levels were significantly associated with more severe depression symptomatology." (PMID 34715912, 2021). "The most significant signals in the KLK8 gene body and in the promoter region were observed in the GSMS cohort, where blood DNAm levels were tested for association with depression symptomatology." (PMID 34715912, 2021). "In this study, we aimed at testing if DNAm levels in the promotor region of KLK8 have clinical applicability in stratifying depression cases based on their depression severity and to distinguish cases from unaffected controls." (PMID 34715912, 2021). "The neurobiology of KLK8 is thus functionally related to that of established biomarkers of depression, like Brain-Derived Neurotrophic Factor (BDNF) and Vascular Endothelial Growth Factor (VEGF)." (PMID 34715912, 2021). "In addition, the inactivation of KLK8 by exercise training or genetic knockout of KLK8 significantly mitigated hippocampal microglial activation, neuroinflammation, and depression-like behaviors in STZ-induced diabetic mice." (PMID 40521191, 2025). "Additionally, running exercise reversed KLK8 upregulation and inactivated Met/Src/Btk/NF-κB signaling pathways, thereby attenuating neuroinflammation, improving neuroplasticity, and alleviating depression-like behaviors in diabetic mice." (PMID 40521191, 2025). "An important implication of hippocampal KLK8 upregulation contributing to CUMS-induced depression-like behavior is that KLK8-targeted therapy may have clinical relevance for patients with depression." (PMID 37076499, 2023). "It was found that CUMS-exposed KLK8 transgenic rats displayed increased depression-like behavioral responses, as evidenced by decreased sucrose preference and longer immobility time in the FST and increased latency to feed in the NSFT, as compared to CUMS-exposed control rats." (PMID 37076499, 2023). "Collectively, our findings suggest that the upregulation of KLK8 may contribute to the pathogenesis of CUMS-induced depression by promoting neuronal apoptosis in the hippocampus." (PMID 37076499, 2023). "Further, exploration of these findings by combining epigenomic, genomic, transcriptomic, and metabolomic data form large cohorts to study depression symptomatology will provide deeper understanding of the role of KLK8 in the molecular pathophysiology of depression phenotypes." (PMID 34715912, 2021). "Our results suggest that blood-derived epigenetic variation of KLK8 is associated with severity of depressed mood among depression cases, but does not allow for stratification of depression cases from controls." (PMID 34715912, 2021). "Our findings suggest that variance in blood DNAm levels in KLK8 promoter region is associated with severity of depression symptoms, but not depression diagnosis." (PMID 34715912, 2021).